IL4R (interleukin 4 receptor)
Diseases named in the same sentence as IL4R in open-access papers (continued):
Sharing a sentence is not in itself a finding about the gene and the disease.
influenza (6 papers, 2009 to 2022). An acute viral infection of the respiratory tract, occurring in isolated cases, in epidemics, or in pandemics; it is caused by serologically different strains of viruses (influenzaviruses) designated A, B, and C, has a 3-day incubation period, and usually lasts for 3 to 10 days. "Our in vivo murine model results highlight the therapeutic potential of IL-4Rα-mediated therapies in asthmatic patients during influenza pandemics." (PMID 33653328, 2021). "Together, these data implicate allergic asthma as a significant risk factor for H1N1-related morbidity and reveal a potential therapeutic role for IL-4Rα signalling blockade in reducing the severity of influenza infection in those with allergic airway disease." (PMID 33653328, 2021). "Taken together, these data show that in OVA-sensitized mice, exposure to DEP prior to infection with influenza enhanced the expression of the TH2 cytokines IL-4 and IL-13 and their common receptor IL-4Rα." (PMID 19682371, 2009).
parasite infection (6 papers, 2013 to 2020). "Numerous studies in allergic airway and parasitic diseases have reported that the classical caMph marker iNOS is increased and the typical aaMph marker Arg1 is decreased in macrophage cell-specific IL-4Rα deficient mice when compared to control groups." (PMID 25790379, 2015). "This apparently contradictory paradigm has been observed in previous studies when examining parasitic infections in IL-4−/− and IL-4R−/− mice." (PMID 33101712, 2020). "Our data reveals a mechanism whereby eosinophil-dependent immunity to the filarial helminth, B. malayi, is locally coordinated by an in situ proliferating pool of Mφ, activated by combination of ligation of IL-4Rα and parasite infection." (PMID 29547639, 2018). "This was done to investigate the possibility that VV-WR infection induced IL-4 and/or IL-13 to up-regulate IL-4Rα expression on naïve bystander CD8+ T cells similar to what has been reported on naïve bystander CD4+ T cells responding to IL-4 following parasitic infection." (PMID 23383283, 2013). "The use of IL-4Rα −/−, IL-13Rα1 −/−, γc −/− and IL-13Rα2 −/− mice have shown that these receptors are indeed important for controlling functions of IL-4 and IL-13 in allergic diseases and parasitic infections." (PMID 23383283, 2013). "No significant increases were apparent in circulating parasitemias at any time-point within IL-4Rα−/−, IL-4Rα−/−CCR3−/−, or IL-4Rα−/−IL-5−/− mice compared with WT controls." (PMID 32571840, 2020).
tuberculosis (6 papers, 2014 to 2025). A chronic, recurrent infection caused by the bacterium Mycobacterium tuberculosis. "Together, we reveal an unappreciated biological function of IL-4Rα signalling in regulating the differential roles of Tregs in listeriosis and tuberculosis." (PMID 39483462, 2024). "Our results demonstrated that the diminished IL-4Rα signalling on Foxp3+ T regulatory cells resulted in a loss of their functionality, leading to survival benefits in listeriosis but not in tuberculosis." (PMID 39483462, 2024). "Hence, the data from IL‐4R KO mice and the data from tuberculosis strongly suggest that both direct tumor killing and an adjuvant immunomodulatory activity are responsible for the DABIL‐4‐mediated therapeutic benefit." (PMID 33682324, 2021). "Besides tuberculosis, mb-1creIL-4Rα-/lox mice during N. brasiliensis infection uncovered that IL-4Rα-responsive B cells-driven IL-13 and antigen processing contribute to T cell-mediated protective immunity." (PMID 34220793, 2021). "Therefore, we hypothesized that the ablation of IL-4Rα signalling on B cells specifically influences the immune response and the outcome of tuberculosis disease." (PMID 34220793, 2021). "Thus, we assessed whether depletion of IL-4Rα on B cells in mb1creIL-4Rα–/lox BALB/c mice in tuberculosis." (PMID 34220793, 2021). "We then asked whether IL-4Rα expression was influenced by M. tuberculosis infection in active TB and TB therapy cohorts." (PMID 39483462, 2024). "In contrast, IL-4Rα-deficient Tregs did not affect the outcome of tuberculosis, despite increased CD4 T-cell responses, reflecting the differential roles of IL-4Rα signalling in Tregs during bacterial infections." (PMID 39483462, 2024). "Even though neutrophils play important roles in the host response to acute tuberculosis, IL-4Rα responsive neutrophils seem not to have essential function in TB pathology." (PMID 25790379, 2015).
ulcerative colitis (6 papers, 2013 to 2024). An inflammatory bowel disease involving the mucosal surface of the large intestine and rectum. "Four (80%) of the associated genes with these CpG sites have been linked to either ulcerative colitis (IL4R and SAA1) or CRC (LAT2 and SAA2)." (PMID 27006956, 2016). "DNA hypermethylation in the promoters of CXCL14, CXCL5, GATA3, IL17C, and IL4R and hypomethylation in the promoters of CCL25, IL13, IL12B, CXCL5, IL4R, IL17A, and IL17RA are associated with the onset or aggravation of ulcerative colitis." (PMID 38473997, 2024). "The potential role of IL-13 signaling independently of IL-4Rα in mediating ulcerative colitis is highlighted as an important consideration when targeting the signaling mechanisms of IL-13 for therapeutic approaches." (PMID 30460209, 2018). "Despite this evidence, recent clinical trial data suggests that specifically blocking the receptor through which IL-13 signals, IL-4 receptor-alpha (IL-4Rα) in ulcerative colitis patients, is insufficient in protecting them from disease outcome." (PMID 30460209, 2018). "Considering that IL-4Rα−/− mice have an exacerbated disease phenotype, we set out to determine if other hematopoietic cell populations expressing IL-4Rα, and prominent in the inflammatory response of ulcerative colitis, play a role in mediating disease." (PMID 32410852, 2020). "In ulcerative colitis (UC) 5 genes (CXCL14, CXCL5, GATA3, IL17C, and IL4R) were hypermethylated compared to healthy controls." (PMID 25526479, 2014).
brain tumor (5 papers, 2002 to 2025). "This enhancement is primarily attributed to the up-regulation of interleukin-4 receptors (IL-4R) on the surface of brain tumor cells." (PMID 39911305, 2025). "Park and colleagues established a novel microbubble–liposome complex conjugated to interleukin-4 receptor (IL4R)-targeting peptide ligands for theranostic treatment of brain tumors." (PMID 33271886, 2020). "It has been reported that human brain tumor cell lines overexpress high plasma membrane interleukin-4 receptors (IL-4R) compared with normal brain tissue." (PMID 23029030, 2012). "Our previous studies have identified abundant expression of receptors for IL-4 (IL-4R) on human brain tumour cells." (PMID 11870521, 2002). "The researchers hypothesized that the presence of the IL4RTP would improve the affinity of the MB-Lipo (DOX) to IL4R-expressing brain tumor cells (U87MG), and attached microbubbles could be used for ultrasound imaging and directed treatment of brain tumors." (PMID 33271886, 2020).
breast tumor (5 papers, 2013 to 2024). "AP1 was previously discovered as an atherosclerotic plaque and breast tumor tissue homing peptide using phage display screening method, and it can selectively bind to the interleukin 4 receptor (IL-4R)." (PMID 24339977, 2013). "For in vivo fluorescence imaging, IL4R-Abx and Ctrl-Abx were conjugated with near-infrared fluorescence dye-labeled IL4RPep-1 and control peptide, respectively, and injected into mice bearing 4T1 breast tumor at the mammary fat pad via the tail vein." (PMID 38646639, 2024). "In addition to 4T1 breast tumor, we investigated tumor homing of IL4R-Abx in two lung tumor models: K-rasLA2mutant transgenic mouse tumor and LLC syngeneic mouse tumor." (PMID 38646639, 2024). "Furthermore, we demonstrated that IL4-Rα expression on CD4+ T cells was required for the TSLP-induced suppression of PyMttg breast tumor growth." (PMID 35657353, 2022). "Test mice were protected against breast tumor growth even in the absence of IL-4Rα on the tumor cells." (PMID 35657353, 2022). "The earlier tumor onset did not translate into reduced survival in mice that lacked IL-4Rα, suggesting that the protective role of IL-4 is mainly in the initiation phase of breast tumor development." (PMID 35657353, 2022). "Mice that lacked IL-4Rα, and therefore could not mount a Th2 immunity, showed very early breast tumor onset regardless of Tslp expression (P = 0.0002 compared with PyMttg group)." (PMID 35657353, 2022).
immune deficiency (5 papers, 2017 to 2023). "The macrofilaricidal efficacy of both OXF and FBZ was reduced in all tested immunodeficient strains, and treatment efficacy was lowest in strains with more severe immunodeficiency, i.e., IL-4r/IL-5−/− vs. ΔdblGata1 mice, or completely abrogated in Rag2/IL-2rγ−/− mice." (PMID 37440891, 2023). "A state of immune deficiency might therefore arise from IL-4Rα targeting as opposed to IL-13 targeting where Th2 responses are optimally elicited." (PMID 28827803, 2017). "Similar microfilaremias were recorded between WT and IL-4Rα−/−, IL-4Rα−/−CCR3−/−, or IL-4Rα−/−IL-5−/− mice, indicating that these immunodeficiencies did not have any impact on mf parasitism in the blood during the first 4 wk of a primary infection." (PMID 32571840, 2020).
leishmaniasis (5 papers, 2012 to 2019). Infectious disease that is transmitted through the bite of hematophagous female phlebotomine sand flies. "Accordingly, we observed reduced IFN-γ expression in the lungs of IL-4Rα-deficient mice at day 14 after infection, pointing to a similar way of action as described for leishmaniasis." (PMID 24475277, 2014). "This is especially relevant when considering the full spectrum of human leishmaniasis and strain-specific roles of the IL-4Rα chain and its ligands." (PMID 29176972, 2017). "This study therefore expands our knowledge on the role of dendritic cells during cutaneous Leishmaniasis and on the effects of IL-4Rα signaling on dendritic cells." (PMID 24204259, 2013). "Another aspect to give consideration to is that immunizing CD11ccreIL-4Rα−/lox mice with IL-4Rα−/− DC resulted in progressive leishmaniasis, showing the importance of IL-4Rα signaling not only in the immunizing DC but also in the host DC." (PMID 22802978, 2012). "In the present study we investigated the role of IL-4Rα-mediated instruction of the vaccinating DC and the host DC during induction of protection against leishmaniasis." (PMID 22802978, 2012). "Our results document the crucial role of IL-4Rα signaling in DC-based vaccination against leishmaniasis by promoting a protective Th1 immune response." (PMID 22802978, 2012). "A complete IL-4Rα-deficient set-up (vaccine and host) showed that IL-4Rα-mediated instruction of DC is important to enhance protection against leishmaniasis, as IL-4Rα-deficient DC were not capable of mediating resistance in CD11ccreIL-4Rα−/lox mice." (PMID 22802978, 2012). "In order to investigate whether IL-4Rα signaling in DC used as vaccine carrier is required to induce protection against leishmaniasis, BMDC were generated from IL-4Rα-deficient BALB/c mice or wt BALB/c mice." (PMID 22802978, 2012). "The results of the present study indicate a direct link between IL-4Rα triggering of BMDC used for immunization and the induction of elevated levels of IL-12 upon L. major infection in BALB/c mice, which mediated complete protection against otherwise lethal leishmaniasis." (PMID 22802978, 2012). "The results show that complete protection against otherwise lethal leishmaniasis required immunization of BALB/c mice with IL-4-responsive BMDC, while IL-4Rα−/− BMDC failed to induce the restriction of lesion development." (PMID 22802978, 2012).
leukemia (5 papers, 2009 to 2025). A malignant (clonal) hematologic disorder, involving hematopoietic stem cells and characterized by the presence of primitive or atypical myeloid or lymphoid cells in the bone marrow and the blood. "Additionally, high expression of IL4Rα in leukemia-associated neutrophils was observed in our study." (PMID 37817276, 2023). "However, the results obtained from this experiment revealed that Treg are responsible for the increase in IL4R expression on leukemia-associated neutrophils." (PMID 37817276, 2023). "Other populations expressing markers of immunosuppressive potential, such as IDO and IL4R, were more frequent at the early stage of leukemia." (PMID 37817276, 2023). "We have shown that EGF4KDEL's cytotoxicity is receptor specific as EGFR-/IL-4R- HPB-MLT leukaemia cells are unaffected by concentrations as high as 10 nM." (PMID 19755995, 2009). "Furthermore, the modification of the tumor microenvironment by induction of the antileukemic immune response and depletion of Treg by DT in DEREG TCL1 leukemia-bearing mice were able to decrease the frequencies of IL4R-expressing neutrophils." (PMID 37817276, 2023). "Interestingly, flow cytometry revealed that the percentage of TCL1 leukemia-associated neutrophils expressing PD-L1 and ARG-1 was increased at the late stage of disease, whereas the percentage of IDO- and IL4R-expressing cells was higher at the early stage." (PMID 37817276, 2023). "In contrast, the progression of leukemia into the spleen correlates with the expression of MHC-II, CD62L, IL4R and PD-L1." (PMID 37817276, 2023). "These experiments revealed that even brief co-incubation of neutrophils with TCL1 leukemia cells altered the expression of CD62L and IL4R." (PMID 37817276, 2023). "Moreover, we assessed which components of the IL4R complexes that are expressed in c-Kit+ leukemia cells, and found that the Il4ra and Il2rg are expressed, but not Il13ra1." (PMID 28819278, 2018).
malaria (5 papers, 2011 to 2024). Malaria is a serious and sometimes fatal disease caused by a parasite that commonly infects a certain type of mosquito which feeds on humans. "The IL1B -5839C and IL4R 1902A alleles are 8.2% and 6.2% respectively more frequent in malaria patients than in controls." (PMID 23217179, 2012). "After population structure correction, only IL1B -5839C > T and IL4R 1902A > G polymorphisms were associated with malaria susceptibility." (PMID 23217179, 2012). "This study investigated gene polymorphisms in the interleukin-4 (IL-4) and its receptor alpha (IL-4Rα) gene regions in human hosts with uncomplicated malaria." (PMID 39482779, 2024). "The IL1B gene -5839C > T and IL4R 1902A > G polymorphisms and IL12RB1 -1094A/-641C and TNF -1031 T/-863A/-857 T/-308 G/-238 G haplotypes were associated with malaria susceptibility after population structure correction (p = 0.04, p = 0.02, p = 0.01 and p = 0.01, respectively)." (PMID 23217179, 2012). "In a gene-based association study with 18 candidate genes for malaria susceptibility using 33 SNPs as genetic markers, this study demonstrated that IL1B, IL4R, IL12RB1 and TNF genes were associated with susceptibility to P. vivax malaria in a population of Pará state, Brazil." (PMID 23217179, 2012). "Befitting any general immune response mechanism, various cytokines may potentially modulate ICAM1 expression, of which we have found evidence for statistical association of IL1, IL4 (and its receptor, IL4R), IL6, IL13, TLR2, TLR4, and IFNG (and its receptor, IFNGR1) polymorphisms with malaria." (PMID 37287037, 2023). "The effects of polymorphisms in a number of genes, including β-globin, G6PD, TNF-α, IFN-γ, CD36, ICAM-1, IL10, IL4R, and LTA, upon the clearance of malaria parasites in African individuals was investigated across five large association studies from Burkina Faso, Cameroon, Kenya, Mali, and Sudan." (PMID 21867552, 2011).
non-small cell lung carcinoma (5 papers, 2021 to 2025). A group of at least three distinct histological types of lung cancer, including non-small cell squamous cell carcinoma, adenocarcinoma, and large cell carcinoma. "Rab1A was significantly associated with IL4Rα expression in non-small cell lung cancer." (PMID 37117331, 2023). "This work has since progressed to a phase 1b clinical trial, where near-complete clinical responses were observed in one of six patients with non-small cell lung cancer (NSCLC) using dupilumab (anti–IL-4Rα) in combination with PD-1/PD-L1 checkpoint inhibitors." (PMID 40367186, 2025). "Repurposing of dupilumab, an IL4R-targeted antibody, has shown promising synergy with immune checkpoint inhibitors in the treatment of non-small cell lung cancer." (PMID 38731867, 2024). "Recent research reported that Rab1A promotes non-small cell lung cancer metastasis by stabilizing the IL4Rα protein." (PMID 37117331, 2023). "Similarly, S100A9(+) inflammatory monocytes in patients with non-small cell lung cancer (NSCLC) are shown to suppress T-cells by production of arginase, iNOS, and the IL-13/IL-4Rα axis." (PMID 33919732, 2021).
ovarian carcinoma (5 papers, 2002 to 2025). A malignant neoplasm originating from the surface ovarian epithelium. "The targeted therapy against IL4R has also been effective in eradicating cancer in a mouse model of orthotopic ovarian cancer." (PMID 40656893, 2025). "Further, ovarian cancers were suppressed by targeting Th2-biased inflammatory response, such as IL-4R-targeted therapies or by using therapies that shift the immunosuppressive Th2 inflammation to the immunostimulatory Th1 type." (PMID 31023965, 2019). "The IL-4 signaling pathway, through its receptor IL4R, may be involved in regulating the immunosuppressive microenvironment of ovarian cancer." (PMID 40656893, 2025). "Furthermore, IL-4 cytotoxin has shown significant anti-tumor activity against IL4R-expressing ovarian carcinoma in a mouse model of ovarian cancer." (PMID 40656893, 2025).
rheumatoid arthritis (5 papers, 2008 to 2014). A chronic, systemic autoimmune disorder characterized by inflammation in the synovial membranes and articular surfaces. "Two IL4R SNPs, rs1805010 and rs1801275, were genotyped in 749 patients from the Consortium for Longitudinal Evaluation of African-Americans with Early Rheumatoid Arthritis (CLEAR) registries." (PMID 20444266, 2010).
anaphylaxis (4 papers, 2015 to 2026). An acute hypersensitivity reaction that occurs from exposure to an allergen. "A genetic predisposition to anaphylaxis has been linked to SNPs in the IL‐4Rα gene." (PMID 41331837, 2026). "We next examined the effect of the IL-4R docking chemical on anaphylaxis." (PMID 40005151, 2025). "After seven subcutaneous injections of dupilumab, the patient was exposed to the culprit mushrooms and exercised at least twice a month without notable anaphylaxis, suggesting that dupilumab may improve allergic reactions in FDEIA patients by blocking the IL-4Rα signaling pathway." (PMID 39364293, 2024).